MIR15A (microRNA 15a)
Synonyms: hsa-mir-15a; MIRN15A; miRNA15A; mir-15a
Gene: MicroRNA gene on chromosome 13 (50,049,119 to 50,049,201, reverse strand). Ensembl gene ENSG00000283785.
Gene Ontology:
Biological process: miRNA-mediated post-transcriptional gene silencing
Cellular component: RISC complex
Homologues: Orthologues: chimpanzee ptr-mir-15a (100% identical), guinea pig MIR15A (100% identical), macaque MIR15A (88% identical), mouse Mir15a (88% identical), pig MIR15A (88% identical), tropical clawed frog xtr-mir-15a (84% identical), zebrafish mir15a-1 (70% identical), zebrafish mir15a-2 (61% identical). Paralogues in human: MIR15B (57% identical), MIR16-2 (45% identical), MIR195 (45% identical).
Diseases named in the same sentence as MIR15A in open-access papers:
MIR15A is named in the same sentence as 5 diseases in open-access papers, as found by Europe PMC text mining. Sharing a sentence is not in itself a finding about the gene and the disease. The quoted sentences say what the papers report.
kidney tumours (1 paper, 2009). "In fact, we found that in lung cancer over expression of BCL2 could be explained by the under expression of MIR15A, MIR16-1, and MIR16-2, while in kidney tumours over expression of DFFB, HTATIP and RELA could be related to the under expression of MIR124A-1, MIR124A-2, and MIR124A-3." (PMID 19402918, 2009).
myeloma (1 paper, 2020). "Recently it was shown that monoallelic deletion of two other genes on 13q which code for Mir15A and Mir16-1 resulted in development of MGUS in wild type C57BL/6 mice and progression of myeloma in the Vk*Myc multiple myeloma mouse model." (PMID 33634031, 2020).
tumour (1 paper, 2017). "Moreover, expression of a number of microRNAs linked to tumour suppression (Mir15a and Mir101b) was increased." (PMID 28811572, 2017).
MIR15A also shares sentences with these, for which no sentence is quoted: B-cell chronic lymphocytic leukemia (1 paper); lung carcinoma (1).